EGFR (epidermal growth factor receptor)
Diseases named in the same sentence as EGFR in open-access papers (continued):
Sharing a sentence is not in itself a finding about the gene and the disease.
squamous cell carcinoma (continued). "Squamous cell carcinoma patients, who had not previously been considered suitable for EGFR-TKI treatment, showed some benefit from treatment with EGFR-TKIs." (PMID 24527088, 2014). "We only found EGFR (8.0%), c-Met (2.8%), and PIK3CA (2.6%) alterations in the non-smoker with squamous cell carcinoma (SCC) subgroup." (PMID 22768234, 2012). "We speculated about a superior efficacy of DTX/RAM treatment in EGFR-positive than in EGFR-negative NSCLC patients, and the reported poor response of squamous cell carcinoma to DTX/RAM treatment may explain the improved survival in the ICI-untreated patients." (PMID 35740634, 2022). "The availability of specific inhibitors of ROS1 and their clinical benefit should lead to simultaneous testing of ROS1 rearrangement with other recurrent biomarkers in NSCLC (e.g EGFR and ALK) in all advanced stage never/light smokers with squamous cell carcinoma and non-squamous NSCLC." (PMID 35303812, 2022). "We showed that the construct could bind to EGFR expressing A431 epidermoid carcinoma cells, and to transiently transformed EGFR overexpressing HEK293T cells and not to EGFR negative control cells." (PMID 30348204, 2018).
prostate carcinoma (760 papers, 1989 to 2026). A carcinoma that arises from epithelial cells of the prostate gland. "Despite these findings, miR-16 is still commonly used as an endogenous qPCR normalizer, even though PCa cell studies show marked down-regulation of miR-16-5p and functional targeting of AR and EGFR, both closely linked to prostate cancer biology." (PMID 41598250, 2026). "Curcumin and beta-phenyl ethyl isothiocyanate (PEITC) treatment caused the prostate cancer line PC-3 to undergo apoptosis, resulting in caspase-3 disruption and the suppression of EGFR- and EGF-induced Akt and PI3K activation." (PMID 40728967, 2025). "Previous research has linked EGFR expression to high-grade, advanced-stage prostate cancer and an increased risk of recurrence, invasion, and bone metastases." (PMID 38739230, 2025). "EGF-induced Ub of EGFR increased in STAP-2-deficient cells but decreased in STAP-2-overexpressing prostate cancer DU145 cells." (PMID 38745775, 2024). "In PTEN-negative prostate cancer cells, the disassembly of HDs leads to the association of plectin with actin-rich focal adhesions, which results in the activation of the EGFR/PI3K/Akt and FAK/Src pathways to promote tumor progression." (PMID 39334817, 2024). "In prostate cancer, EGFR expression is associated with higher Gleason scores and with time to biochemical relapse following radical treatment." (PMID 38730670, 2024). "For example, PD-L1 for monitoring patients undergoing immunotherapy, androgen receptor splice variant 7 (ARv7) for emergence of therapeutic resistance in prostate cancer, and assessing biomarkers such as EGFR, HER2 or PD-L1 in esophageal cancer." (PMID 37051527, 2023). "Other prostate cancer research points to aberrant activation of signaling pathways, such as androgen receptor (AR), epidermal growth factor receptor (EGFR), and inflammation, across races as potential causes of racial difference in incidence and mortality." (PMID 37345032, 2023). "Upregulation of EGFR has been associated with prostate cancer progression and metastasis using various prostate cancer cell line model systems (DU145, PC-3, LNCaP and C4-2B)." (PMID 35493092, 2022). "HLA-A in prostate cancer, MSR1 in familial prostate cancer, and EGFR in both castration-resistant prostate cancer and metastatic castration-resistant had the highest allele frequencies of splice-disrupt variations." (PMID 35286517, 2022). "In our study, the SNPs in EGFR (rs2075110 and rs2075109) were correlated with higher mortality and susceptibility to prostate cancer." (PMID 35741800, 2022). "In cancer cells, hyperactivity of EGFR is linked with androgen independence and metastasis of prostate cancer cells." (PMID 36114463, 2022). "A common genetic aberration that increases during the course of transformation to more malignant prostate carcinomas is a deletion of exons 2–7 of the extracellular domain of EGFR, resulting in constitutively active EGFR variant III (EGFRvIII)." (PMID 34321039, 2021). "Next, we analyzed associations between the survival time of prostate cancer patients and levels of YB-1, EGFR and CXCL14 expression." (PMID 34696665, 2021). "Meanwhile, EGFR was overexpressed and associated with poor prognosis in prostate cancer, and oncogenic transformation by EGFR increased the demand for cholesterol." (PMID 33224867, 2020). "Using single-particle tracking techniques, we found that highly phosphorylated EGFR in the advanced prostate cancer cell line, PC3, was associated with higher EGFR diffusivity, as compared with LNCaP and less aggressive DU145." (PMID 31805710, 2019). "In this study, we explored the connection between prostate cancer metastasis, EGFR dynamics, and underlying molecular mechanisms." (PMID 31805710, 2019). "We had previously shown that over-expression of a protease-dead prostasin in the human prostate cancer cell line PC-3 resulted in a very robust induction of matriptase expression, which was associated with a reduction of the EGFR level." (PMID 28915606, 2017).
prostate carcinoma (continued). "There is increasing evidence that soy has a protective effect on non-small cell lung cancer (NSCLC) cases with epidermal growth factor receptor (EGFR) mutations and breast, ovarian and prostate cancers." (PMID 29033850, 2017). "All PSMA complex components were found assembled in multiple samples of two high-grade prostate carcinomas and associated with EGFR phosphorylation at Y1086." (PMID 27713116, 2016). "We demonstrated the interaction of EGFR to δ-catenin and the effects of this interaction on each of the associated proteins in prostate cancer cells." (PMID 26883159, 2016). "In PCa, hyperactivity of EGFR is linked with androgen independence and metastasis of prostate cancer cells." (PMID 27152724, 2016). "Increased EGFR expression is often detected in prostate cancer, and is associated with poor prognosis." (PMID 26182292, 2015). "The miR-1 was recently shown to be involved in the downstream effects of translocated EGFR signal transduction pathway as tumor suppressor and that loss of miR-1 expression promoted bone metastasis of prostate cancer." (PMID 26807210, 2015). "It is expressed at high levels in prostate cancer and over-expression of EGFR is associated with cancer progression, poor prognosis and development of androgen independence." (PMID 25551444, 2014). "Most importantly, our findings will contribute to a better understanding to further justify the clinical use of EGFR inhibitors in patients with KRAS mutation in prostate cancer." (PMID 25004126, 2014). "Over-expression of EGFR is associated with cancer progression, poor prognosis and development of androgen independence in prostate cancer." (PMID 25551444, 2014). "EGFR function, as judged by Y845 and Y1068 phosphorylations, has also been implicated in the anti-apoptosis of PC-3 prostate cancer cells, for which the combined application of β-phenylethyl isothiocyanate and curcumin leads to apoptotic cell death." (PMID 23702846, 2013). "Enhanced levels of EGFR expression have been associated with the stem cell population in prostate cancer tissue." (PMID 23620784, 2013). "EGFR is a well-studied, versatile signal transducer that is overexpressed in many types of tumour cells, including lung, colon and prostatic carcinoma, and up-regulation of EGFR is associated with poor clinical prognosis." (PMID 24314030, 2013). "Five SNP-SNP interactions in three gene pairs (MMP16+ ROBO1, MMP16+ CSF1, and MMP16+ EGFR) were identified to be associated with aggressive prostate cancer in both groups." (PMID 23593148, 2013). "Our data indicated that higher Mig6 expression was strongly associated with lower levels of EGFR phosphorylation and erlotinib resistance in 6 of 6 head and neck and prostate cancer cell lines assayed." (PMID 23935914, 2013). "Inhibition of EGFR signaling using Gefitinib (Iressa), a tyrosine kinase inhibitor, causes G1 cell cycle arrest and growth inhibition in prostate cancer cells." (PMID 24349321, 2013). "In patient 1, SPINK1 was identified in all 3 CTCs analyzed, and accumulating evidence suggests this defines a subtype of prostate cancer that is susceptible to therapies targeting SPINK1 or EGFR (cetuximab)." (PMID 23145101, 2012). "In prostate cancer, EGFR overexpression is associated with poor prognosis and the transition to CRPC status." (PMID 22454635, 2012). "Our study suggests that high nuclear expression of HIF1α and low EGFR expression in diagnostic biopsies of prostate cancer patients treated with RT ± ADT is associated with a good prognosis." (PMID 22546016, 2012). "We analysed EGFR expression, EGFR mutation status and gene expression profiles of prostate cancer (PC) to supply a rationale for EGFR targeted therapies in this disease." (PMID 21266046, 2011). "More recently, we provided evidence that the epidermal growth factor receptor (EGFR) signalling pathway is implicated as an early event that constitutively activates the PI3K/Akt/NF-κB pathway in PC-3 prostate cancer cells." (PMID 20216540, 2010).
prostate carcinoma (continued). "EGFR is an important signalling protein, and aberrant signalling has been implicated in the pathogenesis of several cancer types, including prostate cancer." (PMID 20808855, 2010). "In cultured prostate cancer cells, down-regulation of epidermal growth factor receptor (EGFR) has been implicated in mediating the antiproliferative effect of the endogenous cannabinoid (CB) ligand anandamide." (PMID 21203460, 2010). "The anti-proliferative effect of anandamide in prostate cancer cells has also been associated with a down-regulation of EGFR expression." (PMID 20808855, 2010). "We and other groups have recently demonstrated an association between the nuclear localization of ErbB3, an epidermal growth factor receptor, and prostate cancer progression." (PMID 19025630, 2008). "The human epidermal growth factor receptor (EGFR) tyrosine kinases are part of a network of pathways which are implicated in the development and progression of prostate cancer, in particular as part of the progression to androgen-independent growth." (PMID 17662137, 2007). "We now attribute this phenomenon to the presence of a variant EGFR (EGFRvIII) that is highly expressed in malignant prostatic neoplasms." (PMID 10638988, 2000). "The epidermal growth factor receptor (EGFR) plays an important role in the development and progression of prostate cancer and its overexpression is associated with decreased survival." (PMID 10360641, 1999). "This approach could be particularly advantageous in prostate cancer, where elevated expression levels of EGFR and B7-H3 are positively correlated and associated with poor clinical outcomes." (PMID 40004194, 2025). "EGFR has been associated with poor prognosis in prostate cancer." (PMID 41124032, 2025). "Interestingly, overexpression of EGFR has been implicated in the metastasis of prostate cancers to the bone." (PMID 38542265, 2024). "Increased EGFR expression seen in prostate cancer is associated with poor prognosis." (PMID 38791037, 2024). "Furthermore, attenuation of estrogen receptor β expression leads to increased EGFR nuclear translocation, which is associated with poor patient outcomes in prostate cancer." (PMID 37461111, 2023). "Our results suggest that, in prostate cancer, increase in clathrin expression is associated with an increased colocalization with EGFR, indicating EGFR recycling may allow cancer to progress through a constitutive proliferative signaling mechanism." (PMID 36869937, 2023). "Instead, KEGG pathway annotation and filtering for proteins associated with “prostate cancer” revealed several proteins, like EGFR, which may help to link DHRS7 to PCa." (PMID 35804847, 2022). "In contrast, reduction of SPRY2 (sprouty homolog 2) expression causes hyperactivation of PI3K/AKT signaling to drive prostate cancer cell proliferation and invasion by enhanced internalization of EGFR and sustained signaling at early endosomes in a PTEN-dependent manner." (PMID 33641663, 2021). "It has been reported that SGLT1 may strongly interact with epidermal growth factor receptor (EGFR), which is overexpressed in more than 80% of the late stages of prostate cancer and is associated with poor prognosis." (PMID 33921222, 2021). "Together with our previous observation that extracellular ATP is an important pro-invasive agent within tumor microenvironment, this may help to elucidate the regulating mechanism(s) underlying EGFR activity in prostate cancer progression." (PMID 26182292, 2015).
prostate carcinoma (continued). "Noticeably, we established a relationship between the effects of Snail associated with Suz12 regulated by EGFR signaling in Ras-activated prostate cancer, and we have deciphered a novel role of miR-203 in regulating SUZ12 expression in prostate cancer via direct interaction with SUZ12 3'UTR." (PMID 25004126, 2014). "Given the critical role of Ras mutation-induced EGFR signaling activation in prostate cancer progression, we hypothesized that EGF-induced autocrine AREG, EREG, and TGFA expression might be directly mediated by miR-203 in RasB1 cells." (PMID 25004126, 2014). "Mutations in EGFR resulting in its ligand-independent activation were reported in prostate cancer." (PMID 23620784, 2013). "In particular, we have found the overactivation of several developmental cascades, such as Hedgehog, EGFR, Wnt/β-catenin and Notch, which was linked with prostate stem cell regulation and the progression of prostate cancer to androgen-independence and metastasis." (PMID 24086245, 2013). "Antibody-mediated inhibition of IGF-1R can result in significant inhibition of tumor growth in both androgen independent and dependent xenograft models and IGF-1R/EGFR crosstalk has been associated with resistance to gefitinib in the well-characterized DU145 prostate cancer cell line." (PMID 24212944, 2011). "NSCLC, for instance, frequently involves KRAS mutations and EGFR pathway alterations, which may interact differently with statin-induced modulation of signalling pathways compared to prostate cancer, where androgen receptor signalling and lipid metabolism are more prominent." (PMID 41163198, 2025). "In the Pakistani population, Hashmi and his colleagues have shown that EGFR under expression was linked to prostatic adenocarcinoma, suggesting it as clinical biomarker in cases with higher Gleason score, high grade and perineural association with prostate carcinoma." (PMID 35456461, 2022). "However, direct inhibition of MEK/Erk1/2 may cause undesirable outcomes, such as augmenting EGFR-driven motility demonstrated in prostate cancer." (PMID 23951036, 2013). "Herein, we demonstrate that anti-human PSMA or EGFR Abs increase in vitro phagocytosis of Myc-CaP (MC) prostate cancer cells expressing human PSMA or EGFR (hPSMA, hEGFR) by macrophages derived from murine p50-IMC." (PMID 39904797, 2025). "The combined effects of luteolin and gefinitib, a selective tyrosine kinase inhibitor that suppresses both EGFR and the kinase activity of cyclin G-associated kinase (GAK), on PC-3 prostate cancer cells were investigated in 2014." (PMID 40728967, 2025). "In genitourinary cancers, TDEVs overexpress disease-specific markers such as prostate-specific membrane antigen (PSMA) and STEAP1 in prostate cancer; EGFR and HER2 in bladder cancer; and carbonic anhydrase IX (CAIX) in kidney cancer." (PMID 41459253, 2025). "p50-IMC combined with PSMA Ab, EGFR Ab (Cetuximab), or fully humanized PSMA.CAR10.3 manifest increased localization to Myc-CaP murine prostate cancer tumors expressing PSMA or EGFR." (PMID 39904797, 2025). "PSMA and EGFR are found on aggressive human prostate cancers, and p50-IMC express receptors that bind the antibody Fc domain." (PMID 39904797, 2025). "Studies on androgen-dependent and androgen-independent prostate cancer cells have shown that curcumin can suppress EGFR activity." (PMID 40728967, 2025). "Yet, there is a shortage of comprehensive investigation to evaluate the modulatory effect of Se compounds on EGFR in prostate cancer." (PMID 38739230, 2025). "The KEGG pathway enrichment analysis revealed several significantly enriched pathways, with particular emphasis on the Hepatitis B, GnRH signaling pathway, EGFR inhibitor resistance, endocrine resistance, and prostate cancer." (PMID 40136517, 2025).